TSPEAR-AS1 (TSPEAR antisense RNA 1)
Synonyms: C21orf31; C21orf90; TSPEAR-AS2
Gene: Long non-coding RNA gene on chromosome 21 (44,506,807 to 44,525,952, forward strand). Ensembl gene ENSG00000235890.
Diseases named in the same sentence as TSPEAR-AS1 in open-access papers:
TSPEAR-AS1 is named in the same sentence as 1 disease in open-access papers, as found by Europe PMC text mining. Sharing a sentence is not in itself a finding about the gene and the disease.
TSPEAR-AS1 shares sentences with these, for which no sentence is quoted: oral squamous cell carcinoma (1 paper).